MFN2 (mitofusin 2)
Diseases named in the same sentence as MFN2 in open-access papers (continued):
Sharing a sentence is not in itself a finding about the gene and the disease.
diabetic nephropathy (9 papers, 2017 to 2026). "The regulatory impact of Mfn2 on PERK can be utilized as a new therapeutic modality for diabetic nephropathy conditions." (PMID 40148800, 2025). "To uncover the underlying molecular mechanisms of genistein on renal protection in diabetic nephropathy, we analyzed changes of mitochondrial membrane potential and assessed the level of mfn2." (PMID 35976278, 2022). "In support, renal biopsies from patients with diabetic nephropathy have shown reduced MFN2." (PMID 38602042, 2024). "Mfn2 has an inhibitory effect on PERK signaling and hence provides anti-apoptotic protection to podocytes in diabetic kidney diseases." (PMID 40148800, 2025). "Recently, a study showed reduced mRNA expression of MFN2, PARKIN, and PINK1 in patients with diabetic nephropathy, which corroborates with our observations." (PMID 29326655, 2017).
Glucose intolerance (9 papers, 2014 to 2023). Glucose intolerance (GI) can be defined as dysglycemia that comprises both prediabetes and diabetes. "Recent data have indicated that hepatic ablation of Mfn2 causes glucose intolerance and deficient hepatic insulin signalling." (PMID 24663492, 2014). "Furthermore, Mfn-2 depletion causes altered glucose metabolism in vivo, as Mfn-2-KO mice developed glucose intolerance, fasting hyperinsulinemia and altered insulin response." (PMID 25566542, 2014). "It has been shown that the ablation of Mfn2 in a mice model results in glucose intolerance, increased hepatic gluconeogenesis, impaired insulin signalling, as well as the development of ER stress." (PMID 37020593, 2023). "Liver-specific ablation of Mfn2 in mice led to numerous metabolic abnormalities, which was characterized by glucose intolerance and enhanced hepatic gluconeogenesis." (PMID 30363990, 2018). "In the second study, mice with liver-specific ablation of mitofusin-2 (Mfn2) developed glucose intolerance, enhanced hepatic gluconeogenesis as well as impaired insulin signaling in the liver and muscles." (PMID 30233495, 2018). "However, combined deletion of both Mfn1 and Mfn2 resulted in severe glucose intolerance (p < 0.005 by one-way ANOVA vs. Ctrl), due to markedly reduced GSIS." (PMID 35487893, 2022). "Also, liver and skeletal muscle deletion of Mfn2 in mice both result in fragmented mitochondrial networks and numerous metabolic abnormalities, including glucose intolerance and enhanced hepatic gluconeogenesis." (PMID 31551926, 2019). "Whereas Mfn1 and Mfn2 individually were dispensable for glucose homeostasis, combined Mfn1/2 deletion in β-cells reduced mtDNA content, impaired mitochondrial morphology and networking, and decreased respiratory function, ultimately resulting in severe glucose intolerance." (PMID 35487893, 2022).
hereditary motor and sensory neuropathy (9 papers, 2013 to 2025). A group of slowly progressive inherited disorders affecting motor and sensory peripheral nerves. "Charcot-Marie-Tooth disease type 2A (CMT2A), the most common axonal form of hereditary sensory motor neuropathy, is caused by mutations of mitofusin-2 (MFN2)." (PMID 27907123, 2016). "Among the identified mutations in the MFN2 gene, three have already been reported in association with axonal hereditary motor and sensory neuropathy (HMSN), namely, the p.(Arg280His), the p.(His20Tyr) and the p.(Thr362Met)." (PMID 39315308, 2024). "SLC25A46 and MFN2 are associated with Hereditary Motor and Sensory Neuropathy (HMSN) while HUWE1 is associated with X-linked syndromic mental retardation, Turner type (XMRT)." (PMID 29342083, 2018). "For example, mutations in PINK1 and Parkin are associated with early-onset forms of Parkinson’s Disease (PD) while mutations in MFN2 are associated with axonal forms of Charcot-Marie-Tooth disease 2 (CMT2) and hereditary motor and sensory neuropathies (HMSN)." (PMID 36339819, 2022). "Hereditary motor and sensory neuropathy VIA with optic atrophy disease (HMSN VIA; Charcot–Marie–Tooth disease type 6A; CMT6A) is an autosomal dominant disease caused by monoallelic pathogenic variants in MFN2." (PMID 36135912, 2022).
lipomatosis (9 papers, 2021 to 2026). A neoplastic process characterized by diffuse overgrowth of mature adipose tissue. "A biallelic missense mutation in mitofusin 2 (MFN2) causes multiple symmetric lipomatosis and partial lipodystrophy, implicating disruption of mitochondrial fusion or interaction with other organelles in adipocyte differentiation, growth and/or survival." (PMID 39739772, 2024). "Humans with biallelic p.Arg707Trp MFN2 mutations develop increased upper body adiposity (multiple symmetric lipomatosis) with lower body lipodystrophy." (PMID 39739772, 2024). "Furthermore, mutations in the mitochondrial fusion gene MFN2 have been linked both to multiple symmetric lipomatosis and to features of MetS, suggesting a potential biological bridge between localized lipoma formation and systemic metabolic disease." (PMID 41409612, 2025). "Whether impairment of other MFN2 functions can also be linked to specific disease pathologies remains to be determined (e.g., lipid droplets and lipomatosis)." (PMID 35399520, 2022). "Finally, the R707W MFN2 variant, which causes CMT2A when present heterozygously, also causes lipomatosis when present homozygously." (PMID 38274408, 2021). "Therefore, multiple symmetric lipomatosis could be, at least in MFN2 and LIPE-related forms, an exacerbated form of partial lipodystrophy." (PMID 35046902, 2021). "In specific genetic forms of partial lipodystrophy, due to MFN2 or LIPE biallelic pathogenic variants, fat overgrowth may lead to massive pseudo-lipomatous regions in upper body and proximal limb areas, leading to the diagnosis of multiple symmetric lipomatosis." (PMID 35046902, 2021). "Homozygous pathogenic variants in MFN2 (HGNC:16877) are associated with Charcot-Marie-Tooth disease type 2A2B (OMIM #617087) and Lipomatosis, multiple symmetric, with or without peripheral neuropathy (OMIM #151800)." (PMID 38622594, 2024). "Consequently, patients with other MFN2‐related phenotypes, such as isolated distal myopathy, amyotrophic lateral sclerosis/frontotemporal dementia (ALS/FTD), or lipomatosis, were not included." (PMID 41030121, 2026).
myocardial ischemia (9 papers, 2018 to 2025). A disorder of cardiac function caused by insufficient blood flow to the muscle tissue of the heart. "In contrast, another report indicates that inhibition of chymotrypsin-like activity of the proteasome by Ixazomib prevents mitochondrial dysfunction during myocardial ischemia by blocking the release of cytochrome c and significantly preserving mitofusin-2 integrity." (PMID 39095788, 2024). "Considering that Hyp treatment in our study upregulated both Mfn1/Mfn2 and Opa1, it is conceivable that strategies aimed at activating mitofusins may complement Opa1-mediated inner membrane fusion to achieve more robust mitochondrial protection in the setting of cardiac ischemia–reperfusion injury." (PMID 40978492, 2025).
Stroke (9 papers, 2020 to 2025). Sudden impairment of blood flow to a part of the brain due to occlusion or rupture of an artery to the brain. "Accordingly, the downregulation of MFN2 aggravates I/R injury in vitro, and a novel MFN2 missense mutation (c.1367C → T) has been associated with early-onset stroke in humans." (PMID 33572080, 2021). "The effects of silencing ATF3 on neurological injury, infarction, adenosine triphosphate (ATP), nicotinamide adenine dinucleotide (NAD+), mitofusin 1 (MFN1) and MFN2 were evaluated in stroke rats." (PMID 40621504, 2025). "There is evidence that MFN2 activation may protect organelles against permeability transition that is closely associated with programmed cell death, interfere with Bax activation, reduce the susceptibility to free radical induced depolarization, and thus play a neuroprotective role in stroke injury." (PMID 35571256, 2022). "Understanding the molecular mechanism of MFN2 in stroke may contribute to have a deeper insight on pathological process of stroke and provides some therapeutic targets for the treatment of stroke." (PMID 35571256, 2022). "The expression of MFN2 in stroke involves a variety of molecular mechanisms." (PMID 35571256, 2022). "For this reason, regulating the Mul2–Mfn2 pathway, either by depleting Mul1 or overexpressing Mfn2, may be a useful therapeutic tool for stroke-induced mitochondrial damage." (PMID 32630218, 2020). "Mechanistically, the expression of LC3B (an autophagy marker) and Drp1 (a mitochondrial fission marker) was increased, whereas that of Mfn2 (a mitochondrial fusion marker) and COX IV (a mitophagy activation marker) was decreased after stroke." (PMID 36254232, 2022). "Ischemia disrupts the dynamic balance of fusion and fission in part by inhibiting expression of fusion proteins MFN2 and OPA1 and recent studies in experimental stroke suggests that inhibition of mitochondrial fission and promotion of fusion is protective." (PMID 36466801, 2022). "Preserving Mfn2 activity together with appropriate MAPK regulation is therefore essential for maintaining mitochondrial quality control, promoting neuronal survival, and may offer a promising therapeutic avenue for mitigating stroke-related brain damage." (PMID 41373489, 2025).
Cerebral ischemia (8 papers, 2020 to 2025). Restriction of arterial blood supply to the brain associated with insufficient oxygenation to support the metabolic requirements of the tissue. "Our research explored how alpinetin influences the expression of p38 MAPK and Mfn2 proteins, given that mitochondrial dynamics can mitigate the damage from cerebral ischemia and oxidative stress." (PMID 41373489, 2025). "Studies have indicated a connection between global cerebral ischemia and the swift migration of Mfn2 from the mitochondria to the cytosol." (PMID 39640236, 2024). "Cerebral ischemia–reperfusion injury results from inadequate autophagy, and Mfn2 has the potential to enhance ischemia–reperfusion injury by boosting the generation of autophagosomes and facilitating their fusion with lysosomes." (PMID 39640236, 2024). "Relative to DG, MFN2 expression significantly (p < 0.05) decreased in CA1 after global cerebral ischemia in mice treated with post-injury MM-control." (PMID 36466801, 2022). "HDAC2 knockout enhances neuronal expression of MFN2 and promotes neuronal survival in mice model of cerebral ischemia-reperfusion injury." (PMID 33609088, 2021). "Nuclear receptor subfamily 4 group A member 1 (NR4A1) inhibition protects against cerebral ischemia-reperfusion induced mitochondrial damage through upregulation expression of MFN2 and reversing MFN2-mediated mitophagy." (PMID 33609088, 2021). "In the rat model of cerebral ischemia/reperfusion injury, the expression of Mfn2 in the cerebral cortex is significantly reduced." (PMID 33424757, 2020). "The protein level of Mfn2 in the mitochondrial fraction decreased after cerebral ischemia and reperfusion in normoglycemic animals." (PMID 33061796, 2020). "It is also found that OPA1 and Mfn2 are reduced in cerebral ischemia, thereby inducing mitophagy." (PMID 33424757, 2020). "Furthermore, GCK treatment could decrease the binding affinity of Mul1 and Mfn2, inhibit Mul1/Mfn2-mediated ubiquitination and degradation, and increase the protein level of Mfn2 in cerebral ischemia-reperfusion injury." (PMID 38650626, 2024). "Our study showed that the expression levels of MFN1, MFN2, and OPA1 protein were downregulated after cerebral ischemia–reperfusion, and 14, 15‐EET treatment inhibited the downregulation of these proteins and promoted mitochondrial fusion." (PMID 37017405, 2023). "Immunofluorescence results showed that the expression levels of Mfn1, Mfn2, and OPA1 were downregulated in mouse cerebral cortex after cerebral ischemia–reperfusion, while 14, 15‐EET treatment reversed this protein downregulation." (PMID 37017405, 2023). "In the context of cerebral ischemia–reperfusion, the lack of Mfn2 hinders platelet activation, formation of prothrombotic platelets, and diminishes the extent of the infarct." (PMID 39640236, 2024). "Cerebral ischemia–reperfusion induces mitochondrial dynamics disorders, upregulates the expression of the mitochondrial division protein Fis 1, and inhibits the expression of mitochondrial fusion proteins MFN1, MFN2, and OPA1, while 14, 15‐EET treatment reverses this process." (PMID 37017405, 2023).
diabetic retinopathy (8 papers, 2020 to 2025). "In diabetic retinopathy, mitochondrial dynamics are impaired with decreased fusion and increased fission; while Mfn2 expression and its GTPase activity are downregulated, Drp1 is upregulated and activated." (PMID 40650203, 2025). "This fusion-fission process is impaired in diabetic retinopathy and the promoter DNA of Mfn2, a fusion gene, is hypermethylated and its expression is downregulated." (PMID 40650203, 2025). "Our aim was to investigate the mechanism of inhibition of Mfn2, and its role in the removal of the damaged mitochondria, in diabetic retinopathy." (PMID 37415667, 2023). "The role of acetylation in the regulation of GTPase activity of Mfn2 in diabetic retinopathy is unclear." (PMID 37415667, 2023). "Acetylation of Mfn2 has dual roles in mitochondrial homeostasis in diabetic retinopathy, it inhibits GTPase activity of Mfn2 and increases mitochondrial fragmentation, and also impairs removal of the damaged mitochondria." (PMID 37415667, 2023). "In diabetic retinopathy, mitochondrial fusion enzyme, mitofusin 2 (Mfn2), is downregulated and mitochondrial dynamic is disturbed resulting in depolarized and dysfunctional mitochondria." (PMID 37415667, 2023). "In diabetic retinopathy, fusion-fission process is dysregulated, while Drp1 is upregulated, Mfn2 is downregulated in retinal vascular cells, and the mitochondria are fragmented." (PMID 37415667, 2023). "In summary, in diabetic retinopathy Mfn2 has an important role in both mitochondrial dynamics and removal of the damaged mitochondria." (PMID 37415667, 2023). "Decreased levels of Mfn2, in addition to impairing mitochondrial dynamics and inhibiting removal of the damaged mitochondria, also increase cell apoptosis; in diabetic retinopathy apoptosis of capillary cells increased." (PMID 37415667, 2023). "Our aim was to investigate the mechanism responsible for inhibition of Mfn2, and the role of Mfn2 in the removal of the damaged mitochondria, in diabetic retinopathy." (PMID 37415667, 2023). "In diabetic retinopathy, while fusion protein mitofusin 2 (Mfn2) is downregulated, fission GTPase dynamin-related protein 1 (Drp1) is upregulated, leading to increased mitochondrial fission." (PMID 35204246, 2022). "In support, our previous work has shown that the mitochondrial fusion protein Mfn2 is also downregulated in retinal microvessels, further confirming the role of mitochondrial homeostasis in diabetic retinopathy." (PMID 35399705, 2022). "In diabetic retinopathy, Mfn2 is downregulated, and its overexpression prevents glucose-induced increase in mitochondrial fragmentation and preserves their functional and genomic stability." (PMID 35399705, 2022). "Compared to nondiabetic donors, while gene and protein expressions of DRP1 were increased by ~ 70% in the retinal microvessels from donors with diabetic retinopathy, MFN2 gene and protein expressions decreased by ~ 40%." (PMID 31938715, 2020). "Thus, protecting Mfn2 activity should maintain mitochondrial homeostasis and inhibit the development/progression of diabetic retinopathy." (PMID 37415667, 2023). "However, intervention of good glycemia directly with DNA methylation inhibitors (Azacytidine or Dnmt1-siRNA), prevented Mfn2 and Mlh1 hypermethylation, and ameliorated retinal dysfunction and diabetic retinopathy." (PMID 32313015, 2020). "Our present data show that retinal microvasculature from donors with diabetic retinopathy have an imbalance in the mitochondrial fusion-fission; they have high levels of mitochondrial fission protein Drp1, and suboptimal levels of the inner membrane fusion protein Mfn2." (PMID 31938715, 2020). "Thus, maintenance of Mfn2 activity, by targeting its acetylation, in addition to preventing impairments in mitochondrial dynamics, has potential to improve clearance of the damaged- fragmented mitochondria, which could inhibit the development/progression of diabetic retinopathy." (PMID 37415667, 2023).
diabetic retinopathy (continued). "Whether Mfn2 has any role in the removal of the damaged mitochondria in the development of diabetic retinopathy is not understood." (PMID 37415667, 2023). "Furthermore, we cannot rule out the possibility that the impairment in the Mfn2-Parkin-ubiquitination axis could also be contributing in the poor removal of the damaged mitochondria in diabetic retinopathy." (PMID 37415667, 2023).
Hepatic steatosis (8 papers, 2016 to 2025). Steatosis is a term used to denote lipid accumulation within hepatocytes. "The inactivation of mitofusin 2 (Mfn2) activity caused by inflammation can have additional deleterious effects on mitophagy, thereby reducing the production of autophagosomes, increasing hepatic steatosis, and accelerating the progression of MASH." (PMID 38132126, 2023). "Mfn2 is also known to participate in ER mitochondria contacts, and Mfn2 deletion in hepatocytes causes hepatic steatosis." (PMID 33276146, 2021). "Previous studies have demonstrated that treatment with the mitochondrial fusion protein mitofusin-2 improves mitochondrial function and reduces hepatic steatosis in mouse models of NAFLD." (PMID 37833939, 2023). "This is in agreement with our data that showed liver-specific knockout of Mfn2 in mice is linked to impaired glucose metabolism, to decreases in SIRT1, SIRT3, and insulin signaling resulting in hepatic steatosis." (PMID 28097021, 2016). "Accordingly, hepatocyte-specific deletion of JNK1/2 protects obese mice from hepatic steatosis, enlarges mitochondria (phenocopying Mfn2 gain of function), and elevates mitochondrial fatty acid oxidation via transcriptional upregulation of mitochondrial proteins." (PMID 33276146, 2021). "Hence, the mechanism by which Mfn2 deletion promotes hepatic steatosis is unclear." (PMID 33276146, 2021). "Future studies will focus on a deeper mechanistic understanding, particularly the roles of Mfn2 and TOMM20 in the regulation of mitochondrial dynamics and lipid metabolism using siRNA technique, to better understand how DHA alleviates fatty liver incidence." (PMID 41345683, 2025). "The study found that the expression level of MFN2 protein decreased significantly in NASH patients, liver steatosis mice and NASH mice; another study found that MFN1 protein expression was significantly reduced in the liver of NAFLD mice." (PMID 36676939, 2022). "Importantly, preventing ER stress in Mfn2 KO livers did not reverse hepatic steatosis, despite increasing fat oxidation." (PMID 33276146, 2021). "This specific role of Mfn2 in VLDL assembly could explain why the reversal of ER stress, inflammation, decreased FAO, and insulin resistance in liver-specific Mfn2 KO mice does not decrease hepatic steatosis." (PMID 33276146, 2021).